OR4C16 (olfactory receptor family 4 subfamily C member 16)
Description:
Odorant receptor.
Synonyms: OR11-135
Tractability: Small molecule: it belongs to a druggable protein family. Antibody: UniProt places it where antibodies can reach, with medium confidence; UniProt predicts a signal peptide or a membrane-spanning region; its Gene Ontology location is reachable by antibodies, with medium confidence.
Gene: Protein-coding gene on chromosome 11 (55,572,128 to 55,573,060, forward strand). Ensembl gene ENSG00000279514.
Subcellular location: Cell membrane
Pathways (Reactome):
Sensory Perception: Expression and translocation of olfactory receptors
Gene Ontology:
Molecular function: olfactory receptor activity; G protein-coupled receptor activity
Biological process: detection of chemical stimulus involved in sensory perception of smell; G protein-coupled receptor signaling pathway
Cellular component: plasma membrane; membrane
Genetic constraint (gnomAD): Loss-of-function variants: 24 observed, 15.37 expected, observed/expected ratio (o/e) 1.56, 90% interval 1.11 to 1.93. The synonymous counts are far from expectation, so gnomAD's model fits this gene poorly and the ratio says little. Missense variants: 659 observed, 372.21 expected, observed/expected ratio (o/e) 1.77, 90% interval 1.66 to 1.89. Synonymous variants: 228 observed, 135.29 expected, observed/expected ratio (o/e) 1.69, 90% interval 1.51 to 1.88.
Homologues: Orthologues: dog OR4C146 (78% identical), dog OR4C137 (77% identical), mouse Or4c29 (77% identical), mouse Or4c104 (76% identical), rat Or4c29 (76% identical), rat Or4c104 (75% identical), mouse Or4c103 (73% identical). Paralogues in human: OR4C11 (67% identical), OR4C12 (55% identical), OR4S2 (54% identical), OR4A15 (53% identical), OR4C15 (53% identical), OR4C46 (52% identical), OR4B1 (51% identical), OR4A47 (51% identical), OR4A5 (51% identical), OR4C45 (51% identical), OR4C13 (50% identical), OR4C3 (50% identical), and 116 more.